CD38 (CD38 molecule)
Diseases named in the same sentence as CD38 in open-access papers (continued):
Sharing a sentence is not in itself a finding about the gene and the disease.
primary immunodeficiency (1 paper, 2022). "Overexpression of hub DEGs (CD38, CDMK2, TBC19) was highly enriched in pathways related to T cell/B cell receptor signaling pathways, primary immunodeficiency, NK cell-mediated cytotoxicity, cytokine–cytokine receptor interaction, and the JAK/STAT signaling pathway (p < 0.05)." (PMID 35359935, 2022).
proctitis (1 paper, 2025). An inflammatory process affecting the anus. "We describe an unusually severe case of syphilitic proctitis in the setting of advanced HIV-related immunosuppression (CD4 39 cells/μL), in which targeted immunophenotyping (ERG and CD38) was a valuable adjunctive tool in the differential diagnosis." (PMID 40700331, 2025).
prolymphocytic leukemia (1 paper, 2018). A mature B- or T- cell leukemia with progressive clinical course. "Interestingly, CD38 is associated with plasmablastic lymphoma and prolymphocytic leukemias." (PMID 29375724, 2018).
prostatic intraepithelial neoplasia (1 paper, 2018). "We have confirmed and extended these findings on a larger cohort of tissue samples, demonstrating that CD38 expression is inversely correlated with disease pathology, from benign prostate tissue to prostatic intraepithelial neoplasia (PIN) to low-grade cancer to high-grade cancer." (PMID 30258629, 2018).
pulmonary embolism (1 paper, 2025). The obstruction of the pulmonary artery or one of its branches by an embolus, sometimes associated with infarction of the lung. "Given that the high doses of intravenously administered EVs increase the risk of fatal pulmonary embolism in mice, CD38‐EVs‐DoxMNs offer a safer alternative of delivery system for targeted EV delivery." (PMID 40317915, 2025). "Additionally, since we reported that intravenously administered EVs could increase the risk of fatal pulmonary embolism in mice, exploring alternative delivery methods for CD38‐EVs beyond i.v routes is essential." (PMID 40317915, 2025).
Respiratory tract infection (1 paper, 2025). An infection of the upper or lower respiratory tract. "The mutation of EARS2 modified protein structure and impaired B-cell function, decreased CD38 expression, and led to dysfunction of mitochondrial metabolism, all of which may account for the recurrent respiratory tract infections and humoral immune disorders observed in LTBL." (PMID 40389993, 2025).
Salmonella Infections (1 paper, 2020). Infections with bacteria of the genus SALMONELLA. "Salmonella infection induced accumulation of circulating interferon (IFN)‐γ‐ and macrophage inflammatory protein 1 β (Mip‐1β)‐ producing CD38+CCR7−CD4+ T cells." (PMID 33135337, 2020).
Seizure (1 paper, 2021). A seizure is an intermittent abnormality of nervous system physiology characterized by a transient occurrence of signs and/or symptoms due to abnormal excessive or synchronous neuronal activity in the brain. "However, HLA-DR− CD38+ Tregs were significantly increased in SAH patients developing seizures during DBI phase compared to EBI phase." (PMID 34244562, 2021). "HLA-DR− CD38+ Tregs were significantly increased during DBI phase compared to EBI phase in SAH patients developing CVS, seizures and infections." (PMID 34244562, 2021).
Senile plaques (1 paper, 2022). Senile plaques are extracellular deposits of amyloid in the gray matter of the brain. "The results showed that intervention with the CD38 inhibitor decreased the number of senile plaques in the hippocampus and cortex of APP/PS1 mice compared to the model group, and the accumulation of Iba1 + microglia decreased." (PMID 35241173, 2022).
sickle cell disease (1 paper, 2020). Sickle cell anemias are chronic hemolytic diseases that may induce three types of acute accidents: severe anemia, severe bacterial infections, and ischemic vasoocclusive accidents (VOA) caused by sickle-shaped red blood cells obstructing small blood vessels and capillaries. "Here, we report that the proportions of Lin-CD34+38- hematopoietic multipotent cells (HMCs) and of Lin-CD34+CD38+ hematopoietic progenitors cells (HPCs) are highly variable between individuals but stable over long periods of time, in both healthy individuals and sickle cell disease (SCD) patients." (PMID 33003401, 2020).
silicosis (1 paper, 2024). Silicosis is a respiratory disease caused by breathing in (inhaling) silica dust. "In contrast, the number of plasma cells (CD38++CD19+/−) was greater in both silicosis groups than in the HC group." (PMID 38891910, 2024).
skin cutaneous melanoma (1 paper, 2021). "Elevated CD38 in patients was associated with skin cutaneous melanoma metastasis." (PMID 34211854, 2021). "However, skin cutaneous melanoma patients with increased CD38 expression showed a significantly higher survival rates of OS and DFS." (PMID 34211854, 2021).
skin sarcoidosis (1 paper, 2024). Formation of non-necrotizing granulomas in the skin. "The results of recent independent studies of patients with skin sarcoidosis also revealed an increase in “naive” B-lymphocytes (CD20+CD27−IgD+) and “transitional” B-cells (CD24++CD38++) in peripheral blood." (PMID 39410592, 2024).
synucleinopathy (1 paper, 2026). A neurodegenerative disease that is characterized by the abnormal accumulation of aggregates of alpha-synuclein protein in neurons, nerve fibers or glial cells. "Considering these data and the low odds ratio for this SNP (~1.1), future studies can explore synergistic effects between CD38 deficiency and phenomena observed in PD such as synucleinopathy, inflammation, and/or oxidative stress." (PMID 41400119, 2026).
T-cell neoplasms (1 paper, 2025). "Building on the success of CD38 targeting in mature T-cell neoplasms, we sought to apply this strategy to CTCL." (PMID 40057636, 2025). "CD38 is a cell surface marker of interest we have previously shown to be upregulated in mature T-cell neoplasms." (PMID 40057636, 2025). "Previously, we demonstrated the preclinical effectiveness of targeting CD38 in mature T-cell neoplasms and we wanted to extend this therapeutic approach to the context of CTCL." (PMID 40057636, 2025).
thymoma (1 paper, 2021). A neoplasm arising from the epithelial cells of the thymus. "Libraries were then panned on cells expressing high levels of CD38, i.e. splenocytes from WT mice and EL4 thymoma cells." (PMID 34539634, 2021).
tumor syndrome (1 paper, 2016). "The patient type would be aged 60 years with a major tumor syndrome, higher lymphocytosis to 150 x 109/L, stage C according to Binet clinical stage, positivity of CD38 and at least one cytogenetic abnormality at biological level." (PMID 27110362, 2016).
urolithiasis (1 paper, 2025). Stone(s) within the urinary tract. "Our finding that B cell traits, Tregs panel, and one trait of CDC panel were linked with increased urolithiasis risk, including IgD-CD24-%lymphocyte, CD24 on transitional B cells, CD25 on IgD+ CD38-naïve, CD4 Treg% T cell, activated and resting Treg AC, and CD11c on myeloid DC." (PMID 40612664, 2025).
tumor (743 papers, 2006 to 2026). "Mechanistically, ADAR1 deficiency in NK cells is accompanied by CD38 expression decline via affecting its mRNA stability, resulting in increased cell mobility, proliferation, and tumor killing capacity." (PMID 41560319, 2026). "We identified a subcluster of CD38+ tumor-associated inflammatory monocytes in the LN2A model that was significantly enriched for activation of the classical and alternative complement pathways." (PMID 40327401, 2025). "In vivo αCD38 antibody treatment led to the loss of CD38 expression in residual tumor cells, highlighting the need for innovative strategies to improve CTCL outcomes despite the CD38 loss in residual tumor cells." (PMID 40057636, 2025). "Excessive lipid accumulation caused by elevated CD36 levels in CD38+ T-cells impairs secretion of anti-tumor factors (IFN-γ, TNF-α)." (PMID 40563926, 2025). "In contrast, tumor-associated samples (gene sets 3 and 4) contained upregulated inflammation-related genes (Tnfrsf9, Fasl, Ccr5) and purinergic pathway genes (CD38, P2rx7)." (PMID 41279375, 2025). "In a study of tumor-induced senescent macrophages, senescent macrophages were found to express high levels of CD38 along with increased expression of Arg1, which is associated with decreased T cell reactivity." (PMID 39781471, 2025). "A common feature of all immunosuppressive cells, including regulatory B cells (Bregs) and tumor-associated macrophages (TAMs), is the expression of high levels of CD38, which can be targeted by CD38 mAbs." (PMID 41567224, 2025). "Although CD38 monoclonal antibodies inhibited the proliferation and survival of tumor cells, they also caused substantial side effects on anti-tumor NK cells." (PMID 40649955, 2025). "A higher number of CD38 + cells in the tumor was strongly associated with a favorable response to Immune-checkpoint blockade in HCC, implying longer median progression-free survival and median overall survival." (PMID 40382743, 2025). "Numerous studies have associated its presence with the aggressive progression of the disease because in CLL, a proliferating tumor cell demonstrates elevated levels of CD38 expression, while others have linked it to early-stage disease (Rai stages 0-II)." (PMID 39329950, 2024). "Our current work shows that lactate, which is caused by tumor metabolism remodeling, upregulates the expression of CD38 through the Hippo‐TAZ pathway." (PMID 38545257, 2024). "From a clinical perspective, we found that the levels of CD8+CD28+ T, NK, and CD8+CD38+ T cells were associated with tumor characteristics and liver function, which, to some extent, would explain their prognostic value." (PMID 38404585, 2024). "In this sense, studies by other authors have demonstrated that response to daratumumab is significantly associated with levels of CD38 on tumor cells, and that MM cells from patients at the time of progression have low CD38 expression levels." (PMID 38731936, 2024). "The presence of IL-17 increases tumor resistance by upregulating CD38, while IL-22 is associated with EMT, strengthening tumor invasiveness and metastasis." (PMID 37680632, 2023). "We found that inhibition of B7-H3 in mouse models with high mTORC1 activity inhibits tumor growth, associated with increased infiltration of cytotoxic CD38 and CD39-double-positive CD4+ T cells and increased IFN-γ responses and MHC-II expression." (PMID 36869048, 2023). "A higher number of CD38-positive tumor-infiltrating plasma cells was associated with a significantly longer MFS and BRCA mutations." (PMID 37894900, 2023). "Our previous report has shown an association of CD38+ tumor-infiltrating leukocytes (TIL) with HCC prognosis and identified CD3+ T cells and monocytes as the dominant CD38-expressing immune populations among the TILs." (PMID 37377962, 2023). "A higher density of CD38+ tumor-associated macrophages (TAM) has been associated with improved prognosis and better response to PD-1/PD-L1 therapy in HCC." (PMID 37377962, 2023).
tumor (continued). "Abnormally elevated CD38 expression in T‐ALL and T‐LBL is associated with tumor expansion and disease development, making CD38 a potential target for anti‐T‐ALL and T‐LBL treatment." (PMID 35106962, 2022). "Culture of PD-L1 expressing human epithelial breast cancer cells with B cells can induces the development of CD24+CD38+Bregs, which are associated with increased tumour grade and higher frequency of Tregs in patients with invasive breast cancer." (PMID 35350071, 2022). "It has an entirely different antigen-binding epitope compared to Daratumumab, which can almost completely inhibit the enzymatic activity of CD38 and directly cause the apoptosis of tumor cells through FcγR-mediated cross-linking." (PMID 35978433, 2022). "In vitro and ex vivo experiments showed that this drug induces tumor lysis by T-cell activation, even in samples from patients with high-risk cytogenetics and prior exposure to anti-CD38 moAb." (PMID 36009041, 2022). "The transplant of CD34+CD38− subpopulation into severe combined immuno-deficient (SCID) mice developed more tumor growth than CD34+CD38+ or CD34− subpopulations." (PMID 36230480, 2022). "According to previous literature, CD38 expression is associated with M1 macrophages, which produce pro-inflammatory cytokines and exert anti-tumor effects." (PMID 36224603, 2022). "Daratumumab is a human IgGK monoclonal antibody targeting CD38 with tumor activity associated with immunomodulatory mechanism." (PMID 35846211, 2022). "Because of the high risk of on-target/off-tumor toxicity occurring with targeting CD38, Drent and colleagues introduced a “safety-switch” in their affinity-optimized CD38 CAR T-cell product." (PMID 35199207, 2022). "Expression of CD38 on the surface appears to correlate with aggressiveness of the tumor and, in de novo DLBCL, high CD38 expression is associated with significantly worse progression-free survival and poor overall survival." (PMID 36139103, 2022). "Abnormally elevated CD38 expression in T‐ALL and T‐LBL is associated with tumor expansion and progressive disease, making CD38 a potential target for anti‐T‐ALL and T‐LBL treatment." (PMID 35106962, 2022). "CD38-deficient animals also show reduced tumor formation, attributed to the lack CD38-mediated immunosuppression." (PMID 34421911, 2021). "An appropriate vaccination strategy combining neoantigen peptide-pulsed DC with anti-CD38 antibody can render an ICT-resistant “cold” tumor susceptible to immune rejection via a mechanism involving neutralization of regulatory T cells." (PMID 34771674, 2021). "Nevertheless studies performed in CD38 deficient mice showed attenuated tumor size, progression, and improved life expectancy." (PMID 33727923, 2021). "Assessment of CD38 in tumor stroma showed that higher number of CD38+ cells positively associated with the TN group (p = 0.02)." (PMID 33416944, 2021). "The cells with CD34++ CD38− cell-surface antigen were only 0.2% in the tumor but had the potential to form neoplasms in the immune-deficient mice." (PMID 34359786, 2021). "The results revealed that CD38 was strongly linked to immune infiltration of HNSCC, indicating that CD38 in tumor microenvironment and circulating lymphocytes is linked to immune imbalance." (PMID 34211854, 2021). "In mouse models, inhibition of CD38 restricted primary tumor growth and was associated with lower rates of pulmonary and brain metastasis as a result of promoted cell death, reduction in cancer-associated fibroblast, and prevention of angiogenesis." (PMID 33727923, 2021). "Our results showed that all of TRPM2-deficient A549 tumor cells exhibited a significant reduction of tumor burden compared with that of control but independent on the expression of CD38." (PMID 34226519, 2021). "Consist with precious studies, we also demonstrated that tumor growth was dramatically inhibited in the CD38 deficiency mice in comparison with that of control WT mice." (PMID 34226519, 2021).
tumor (continued). "NAD+ is produced by the salvage pathway in hypoxic TME, which is further converted to adenosine by CD38-expressing cells, thus further suppressing the immune response by recruitment of MDSCs, Tregs, tumor associated macrophages (TAMs)." (PMID 33727923, 2021). "Daratumumab is an IgG1 humanized mAb that recognizes overexpressed antigen CD38 in MM tumor cells, causing their death through antibody-dependent phagocytosis, complement-dependent cytotoxicity, blocking of CD38, and ADCC." (PMID 33919155, 2021). "The accumulation of adenosine within the TME causes immune suppression; targeting CD38 enzymatic activity would largely influence tumor cells." (PMID 33727923, 2021). "As target cells we used CD38-expressing as well as CRISPR/Cas9-generated CD38-deficient tumor cell lines (CA-46, LP-1, and Daudi) transduced with firefly luciferase." (PMID 32013131, 2020). "The adverse prognosis associated with CD38 expression is likely related to increased proliferation rate of tumor cells, which become more susceptible to accumulation of pathogenic genetic lesions." (PMID 32225002, 2020). "The GSEA and correlation analyses in our study implied that CD38 regulated the tumor immune microenvironment in EOC and was associated with B- and T-cell activation and regulated immune responses." (PMID 32425977, 2020). "CD38 CAR T-cells reduced the tumor burden in bone marrow and blood but caused uncontrollable cytokine release syndrome (CRS)." (PMID 33643279, 2020). "Deletion of the Cd38 gene reduced tumor formation in both Arh1-deficient and wild-type mice, with significant reductions in the incidence of lymphomas, adenocarcinoma, and hemangio/histolytic sarcomas." (PMID 32092898, 2020). "In these tumor models, suppression of CD38+ cancer cells associate with an increase in T-helper and cytotoxic T lymphocytes, T-cell functional response and TCR clonality." (PMID 31402913, 2019). "Along with the detrimental effects associated with depletion of microenvironmental NAD, CD38 generates second messengers associated with calcium signaling, resulting in an increased amount of NO that favors tumor growth." (PMID 31130949, 2019). "Lastly, these studies demonstrated that CD38 activity increases pAMPK with subsequent inhibition of fatty acid and lipid synthesis, so loss of CD38 with tumor progression correlates with decreased pAMPK and increased fatty acid/lipid synthesis." (PMID 31878283, 2019). "Despite these positive results, loss of expression of the target antigen (CD38) remains as an important problem associated to daratumumab treatments, as tumor cells stop responding to the therapy." (PMID 30445802, 2018). "Since CAFs and blood vessels are known to facilitate tumor growth, it is possible that the inhibitory effect of loss of CD38 is mediated, at least partially, by reducing the amount of these tumor-supporting TME components." (PMID 30159123, 2018). "As described in the previous section, FcγR polymorphisms have a modest impact on efficacy of CD38 antibodies to eliminate tumor cells." (PMID 30294326, 2018). "After transplantation into mice with severe combined immune deficiency (SCID), these CD34+/CD38− cells can form tumors that phenotypically resemble the patient’s original tumor, indicating that they are tumorigenic." (PMID 23443123, 2012). "These targets may include tumor-associated antigens such as CD38, which is recognized by Daratumumab in multiple myeloma, or immune checkpoint ligands such as PD-L1, targeted by Atezolizumab." (PMID 41462483, 2025). "Additionally, multiplexed immunofluorescence results indicated that the density of CD38 + tumor-infiltrating immune cells is associated with reduced survival and immunosuppressive mechanisms in the tumor microenvironment." (PMID 40382743, 2025).